DRD2 (dopamine receptor D2)
Diseases named in the same sentence as DRD2 in open-access papers (continued):
Sharing a sentence is not in itself a finding about the gene and the disease.
Anxiety (100 papers, 2002 to 2026). Intense feelings of nervousness, tension, or panic often arise in response to interpersonal stresses. "The aim of the study: To examine the relationship of cannabinoid dependency in the genetic context—the association between the rs1799732 polymorphism of the DRD2 gene and psychological traits and anxiety." (PMID 36078646, 2022). "The potency observed for this factor was 76%, and the polymorphism of the DRD2 gene explained approximately 2% of rs1799732 and cannabis dependence or lack thereof on trait anxiety score variance." (PMID 36078646, 2022). "As a result, in the analysis based on each gene, trends for association were observed between State Anxiety and the DRD2-141C Ins/Del polymorphism and between Trait Anxiety and the DRD2 Ser311Cys or TH PstI site polymorphism." (PMID 34440393, 2021). "The model 2 × 3 factorial ANOVA of the addicted subjects and controls was performed, and the DRD2 rs1076560 variant interaction was found for the anxiety state and trait scales, and for the NEO-FFI Neuroticism scale." (PMID 32365807, 2020). "This is plausible given that mice deficient for the long isoform of DRD2 (D2LR) are reported to show anxiety-like and depressive-like behaviors only following a stress-exposure paradigm." (PMID 33214315, 2020). "Among those, we observed genes that have been associated with PTSD in previous human studies (e.g., DRD2 and HTR2a) or linked to anxiety or PTSD-like behaviors in humans or animal models (Igf2, Grm2, Clock, Trhr)." (PMID 30705647, 2018). "The genes CCK, POMC, MCHR1, GABRA6, HTR2A and DRD2, which associated with heat score in at least one brain area, are known to modulate emotional states like anxiety and satiety or even sexual motivation." (PMID 21504592, 2011). "Finally, combinations of ADORA2A and DRD2 polymorphisms have been reported, which account for more variation in caffeine‐induced anxiety compared to when they are isolated from each other." (PMID 41549915, 2026). "Finally, a recent study identified a polymorphism in the DRD2 gene as related to both anxiety and neuroticism scores in patients with polysubstance use disorder." (PMID 37937232, 2023). "Then, we pharmacologically validated the role of DRD2 in the BLA and found that the activation of DRD2 in the BLA caused anxiety-like behaviors under physiological conditions, but the administration of a DRD2 antagonist or EA stimulation alleviated anxiety in naive mice." (PMID 35696012, 2022). "Interestingly, the Drd2 A1 allele, a Drd2 gene polymorphism, which causes lower Drd2 expression levels in the brain, has been associated with anxiety and depression." (PMID 34750364, 2021). "In the analysis based on each gene, trends for association were observed between State Anxiety and the DRD2 -141C Ins/Del polymorphism (p = 0.031, uncorrected), and between Trait Anxiety and the DRD2 Ser311Cys or TH PstI site polymorphism (p = 0.048 and 0.041, respectively, uncorrected)." (PMID 17018139, 2006). "The current research suggests that DRD2 can activate the self-regulated synaptic pruning mechanism through the mTOR signaling pathway, and the deficiency of synaptic pruning in adolescents results in hyperglutamate function and anxiety-like behavior in adulthood." (PMID 37274216, 2023). "The study concentrated on analysis of three polymorphisms located in the dopamine receptor 2 (DRD2) gene—rs1076560, rs1799732 and rs1079597 using the PCR method, personality traits determined with the Big Five Questionnaire, and anxiety measured with the State Trait Anxiety Inventory." (PMID 31948125, 2020). "Chemogenetic activation of these Drd2+ neurons was sufficient to induce anxiety-like behaviors, whereas overexpression of Kir4.1 hyperpolarized the Drd2+ neurons and significantly reduced anxiety-like behaviors in the PWSI rats." (PMID 40001468, 2025).
Anxiety (continued). "SLC6A4, SLC6A2, and DRD2 are known to be involved in the serotonergic and dopaminergic systems, which impact the perception of exercise-induced fatigue and anxiety." (PMID 39200631, 2024). "Remarkably, the most pleiotropic effect was identified for the DRD2 gene of the dopaminergic core set, encoding the DA receptor D2, which was associated with OUD, SUD, anxiety, irritability and neuroticism." (PMID 37937232, 2023). "Neurotrophin and neurotransmitter receptors: Neurotrophic factor such as brain-derived neurotrophic factor (BDNF) and anxiety-related neurotransmitters such as serotonin receptor 5HT1A, dopamine receptor Drd2 in the PFC were examined." (PMID 37407491, 2023). "Here, we used western blotting to examine the expression of DRD1 and DRD2 and pharmacological regulation combined with behavioral testing to detect anxiety-like behaviors." (PMID 35696012, 2022). "Previous studies have suggested that both DRD1 and DRD2 regulate anxiety, but they do so through different mechanisms." (PMID 35696012, 2022). "In the pathological state, antagonization of DRD2 in the BLA or EA treatment alleviated SNI-induced anxiety-like behaviors, and EA inhibited anxiety-like behaviors by antagonizing DRD2 in the BLA." (PMID 35696012, 2022). "After quinpirole and the DRD2 antagonist sulpiride were injected into naive mice, their anxiety-like behaviors were relieved to an extent equal to that of EA treatment combined with quinpirole treatment." (PMID 35696012, 2022). "To verify the key role of DRD2 activity in the BLA in anxiety-like behaviors, we also used pharmacological methods to test this role in naive mice and examined the anxiety-like behaviors of each group." (PMID 35696012, 2022). "We observed that injection of the DRD1 antagonist SCH23390 or the DRD2 agonist quinpirole into the BLA contributed to anxiety-like behaviors in naive mice." (PMID 35696012, 2022). "There was a statistically significant effect of DRD2 genotype interaction rs1799732 and addiction to cannabis or its absence (control group) on the trait anxiety scale score (F2.507 = 4.39; p = 0.013; η2 = 0.017)." (PMID 36078646, 2022). "Naive mice injected with the DRD2 agonist quinpirole in the BLA exhibited anxiety-like behaviors on days 15 and 17, as the time spent in the open arms and central area was significantly decreased." (PMID 35696012, 2022). "Taken together, these results demonstrate that inhibition of DRD2 in layer 5 of ACC during adolescence leads to elevated anxiety-like behaviors in adulthood." (PMID 34750364, 2021). "Migraine and anxiety have been associated with the serotonin transporter gene 5-HTTLPR polymorphism and the C/C NcoI polymorphism within the dopamine receptor D2 gene." (PMID 31072313, 2019). "The result showed significant association between caffeine-induced anxiety and specific ADORA2A polymorphism (rs5751876, rs2298383, rs4822493) and DRD2 polymorphism (rs1110976)." (PMID 31435520, 2018). "The magnitude of the effect was similar to that observed when Kalirin expression was eliminated in all neurons, suggesting an important contribution of Kalirin expressed in Drd2-expressing neurons in normally suppressing anxiety-like behavior." (PMID 28535798, 2017). "DRD1 and DRD2 in the BNST regulate anxiety, fear, and addiction." (PMID 39841059, 2025). "Carriers of the T allele of DRD2 957T showed lower interpersonal stress, anxiety, and ADHD symptoms than non-carriers, with ts (18.48 to 85.86) = −4.01 to −2.13, and p = 0.001 to 0.047." (PMID 35328003, 2022). "EA also activated DRD1 or inhibited DRD2 in the BLA to alleviate anxiety-like behaviors." (PMID 35696012, 2022). "Moreover, E3 treatment had marked neurological effects, notably reduced the anxiety levels of both male and female offspring, accompanied by a significant decrease in DRD2 expression and activity." (PMID 35491423, 2022). "DRD2, a DR, has been reported to be involved in anxiety-like behaviors." (PMID 35696012, 2022).
Anxiety (continued). "We found that both activation of DRD1 and inhibition of DRD2 could alleviate SNI-induced anxiety-like behaviors, and EA had a similar effect of alleviating anxiety." (PMID 35696012, 2022). "Carriers of the T allele of DRD2 C957T and the A1 allele of DRD2 Taq1 showed lower anxiety scores than non-carriers, with t (18.85) = −2.52, and p = 0.02." (PMID 35328003, 2022). "EA alleviates SNI-induced anxiety-like behaviors by inhibiting DRD2 in the BLA." (PMID 35696012, 2022). "EA alleviates anxiety-like behaviors by activating DRD1 or antagonizing DRD2 in the BLA." (PMID 35696012, 2022). "The analysis was carried out by comparing the polymorphism in the DRD2 gene and personality traits measured by the Big Five Questionnaire (NEO FFI) and anxiety measured by the Anxiety Trait Inventory (STAI) in two study groups—cannabis-dependent and non-addicted." (PMID 36078646, 2022). "In addition, DRD2 was the common target among “Jun,” “Chen,” “Zuo” and “Shi” medicines, and the activation of DRD2 was found to potentially limit, such as anxiety, dizziness, serious digestive problems, agitation, and so on." (PMID 35280511, 2022). "We then used the SR-Drd2+/− rats to investigate the roles of Drd2 in synapse development in anterior cingulate cortex (ACC), a brain region implicated in emotional symptoms of neuropsychiatric diseases such as anxiety and depression." (PMID 34750364, 2021). "Within our family constitutive activation of the G protein‐dependent pathway may give a potential explanation for the psychiatric symptoms of generalized anxiety and panic attacks as the current main treatment for psychiatric diseases are DRD2 antagonists." (PMID 33200438, 2021). "Finally, differential deletion of SHANK3 either affecting DRD1- or DRD2-positive neurons (ex4-22|ALL-Drd1Cre or -Drd2Cre) resulted in a minor anxiety-like phenotype and increased repetitive behavior, respectively." (PMID 34784886, 2021). "Sequencing of RNA collected from Drd2 neuron ribosomes revealed genes dynamically regulated following fear conditioning, many of which have been previously reported to be involved in fear and anxiety-like behaviors." (PMID 30135420, 2018). "Interestingly, the Drd2-Cre mice showed mildly elevated locomotor activity at baseline, which correlates with the decrease in anxiety-like behavior observed in Drd2-Cre mice." (PMID 28535798, 2017). "Furthermore, pubertal exposure to DEHP at doses ranging from 1–200 mg/kg decreased dopamine receptor D2 protein in the striatum of adult female mice, accompanied by significant alterations of social and anxiety-like behavior." (PMID 28199414, 2017). "At the end of the 12-week experiment, anxiety-like behavior was evaluated by the light/dark box test; compulsive-like behavior by Marble burying, transcriptional regulation of genes Lrrk2, Tlr4, Nfat, Drd1, Drd2, Il6, Il1β, Il10, and iNOS by RT-qPCR; and inflammatory markers by flow cytometry." (PMID 37063320, 2023). "Moreover, we speculated that EA relieved anxiety-like behaviors in SNI mice by antagonizing DRD2 in the BLA." (PMID 35696012, 2022). "Second, reduction of neurogenesis- and anxiety-related neurotransmitters such as BDNF, 5HT1A and Drd2 in the PFC was observed." (PMID 37407491, 2023). "In conclusion, we have demonstrated a novel mechanism by which DRD1 and DRD2 in the BLA play different roles in neuropathic pain-induced anxiety-like behaviors through decreased DRD1 and increased DRD2." (PMID 35696012, 2022). "Overall, these results suggest that both inhibiting DRD2 in the BLA and EA treatment attenuate SNI-induced anxiety-like behaviors." (PMID 35696012, 2022). "EA alleviated anxiety-like behaviors to an extent similar to that of the DRD1 agonist and DRD2 antagonist." (PMID 35696012, 2022). "To further demonstrate the role of DRD1 and DRD2 in the BLA in spared nerve injury (SNI) model-induced anxiety-like behaviors, we injected the DRD1 agonist SKF38393 or the DRD2 antagonist sulpiride into the BLA." (PMID 35696012, 2022).
Anxiety (continued). "Our study demonstrated that the protein levels of DRD1 were significantly decreased and those of DRD2 were increased in the AMY after SNI surgery, which suggested that DRD1 and DRD2 in the AMY have opposite effects on anxiety behaviors." (PMID 35696012, 2022). "Intriguingly, the rats spent lesser time in the light box and open arm after inhibition of DRD2 in layer 5 of ACC during 3–4 weeks old, indicating elevated anxiety-like behaviors." (PMID 34750364, 2021). "Lastly, inhibition of Drd2 in the ACC during adolescence lead to hyperglutamatergic function and anxiety-like behaviors in adulthood." (PMID 34750364, 2021). "Deficits of Drd2-mediated synaptic pruning in the ACC during adolescence lead to hyper-glutamatergic function and anxiety-like behaviors in adulthood." (PMID 34750364, 2021). "We lastly illustrate that inhibition of DRD2 in the ACC during adolescence leads to hyperglutamatergic function and anxiety-like behaviors in adulthood." (PMID 34750364, 2021). "Naïve Grp-/- mice displayed normal anxiety and pain sensitivity, consistent with normal expression of immediate-early genes (IEG; c-Fos and Arc) and dopamine-related genes (Drd1, Drd2, Th and Nurr1) in the BLA and VTA of naïve Grp-/- mice." (PMID 39580604, 2025). "Intra-BLA administration of DRD1 antagonist or DRD2 agonist in naive mice induced anxiety-like behaviors, with no change in PWTs." (PMID 35696012, 2022). "Electroacupuncture (EA) is commonly used to treat chronic pain and emotional disorders, but it is still unclear whether EA plays a role in analgesia and anxiety relief through DRD1 and DRD2 in the BLA." (PMID 35696012, 2022). "Both activating DRD1 and antagonizing DRD2 in the BLA attenuated SNI-induced anxiety-like behaviors, but neither had an effect on mechanical allodynia." (PMID 35696012, 2022). "Many genes, such as ADORA2A, NPY, DRD2, GABRB3, has shown relation with panic disorder in few studies, with supporting evidence of each gene having relation with panic disorder or, in part, anxiety related function." (PMID 31435520, 2018). "A vast literature has emphasized the role of DRD2 in addiction; but significant evidence also suggests PENK involvement in mood/reward regulation and anxiety that are often correlated with alterations of the mesocorticolimbic system and the striatopallidal circuitry in aversive behavior." (PMID 22745721, 2012). "Dopamine receptor D1 (DRD1) and dopamine receptor D2 (DRD2) in the basolateral amygdala (BLA) have been implicated in mediating anxiety-related behaviors, but their potential roles in the BLA in neuropathic pain-induced anxiety have not been examined." (PMID 35696012, 2022). "However, a potential role of DRD1 and DRD2 in the BLA in neuropathic pain-induced anxiety has not been examined in the spared nerve injury (SNI) model." (PMID 35696012, 2022). "Both overexpression of DRD1 and optogenetic stimulation of DRD1, but not DRD2, within the PFC, have shown similar reductions in anxiety-like behavior, as indicated by a higher number of open arm entries in the elevated plus maze." (PMID 38611750, 2024). "Of note, inhibition of DRD2 in layer 5 of ACC between 7- and 8-week-old age did not affect locomotion, anxiety-like, or social behaviors." (PMID 34750364, 2021).
psychosis (86 papers, 2010 to 2025). "It was shown that the T allele of DRD2 rs1076560 was associated with a threefold greater likelihood of psychotic disorders, compared to the carriers of the GG genotype (OR = 3.07; 95% confidence interval [CI]: 1.22–7.63)." (PMID 35457347, 2022). "Haloperidol and penfluridol are hydroxypiperidine-based anti-psychotic drugs that are employed to control symptoms associated with several psychotic disorders, mainly through the blockade of dopamine D2 receptor (DRD2)." (PMID 34439102, 2021). "We have noted associations between two DRD2 polymorphisms and cognitive function that differ depending on the presence of familial or clinical risk for psychotic disorders." (PMID 26114663, 2015). "Individuals carrying the DRD2 T allele or the AKT1 C allele have an increased psychosis risk in the context of cannabis use; however, the risk is especially increased in subjects who carry ‘risk’ alleles from both genes." (PMID 27336035, 2015). "Using linear regression, we compared the associations between cognitive performance and two candidate DRD2 polymorphisms (rs6277 and rs1800497) between subjects having familial (n=61) and clinical (n=45) risk for psychosis and a random sample of participating NFBC 1986 controls (n=74)." (PMID 26114663, 2015). "AKT1 signalling cascade affects dopamine 2 (D2) receptors, encoded by the DRD2 gene, known to play a key role in psychosis and decreased AKT1 expression could result in an increased level of synaptic activation through the inhibitory effects from dopamine binding on the enzyme." (PMID 34573260, 2021). "Moreover, DRD2 is associated with learning the motor sequences and the motor components of several psychiatric disorders such as motor defects related to the first episode of psychosis." (PMID 32411272, 2020). "Specifically, SNPs at the DRD2 gene may indicate risk for psychomotor factor performance in those with familial risk for psychosis and for verbal factor performance in those at familial and clinical risk for psychosis." (PMID 26114663, 2015). "The effect of two DRD2 SNPs on cognitive performance may differ according to risk type for psychosis, suggesting that cognitive intermediate phenotypes differ according to the type (familial or clinical) risk for psychosis." (PMID 26114663, 2015). "Among the 170 propsychotic target genes, 8 were a high-confidence psychosis risk gene (GRIN2A, DRD2, CYP2D6, CHRNB4, CHRM4, GABBR1, GRM3, CHRNA3)." (PMID 40701976, 2025). "In contrast, DRD1 and 5HTR2C were DEGs for the psychosis and agitation domains while the psychosis domain also demonstrated DRD2 and DRD4 as DEGs." (PMID 38575567, 2024). "Classical antipsychotics, such as chlorpromazine and perphenazine, are potent dopamine D2 receptor (DRD2) antagonists that are effective in treating the positive symptoms of psychosis." (PMID 38317588, 2024). "This study was to evaluate dopamine receptor D2 availability in the striatum (caudate/putamen) in recently abstinent cannabis dependent users after recovery from psychosis in comparison with abstinent MDMA “ecstasy” abusers and healthy control participants." (PMID 37965367, 2023). "Disturbed dopamine function is important for psychosis, and most antipsychotic treatments target DRD2-like dopamine receptors (DRD2, DRD3, DRD4)." (PMID 37031222, 2023). "The aim of this study was to evaluate dopamine receptor D2 availability in the striatum (caudate/putamen) in abstinent cannabis users after recovery from cannabis-induced psychosis." (PMID 37965367, 2023). "A key next step is thus to explore the effect of the DRD2-Polygenic Co-expression Index on dopamine function in disorders where involvement of the dopamine system has been demonstrated, such as psychosis, addiction, bipolar disorder." (PMID 35871219, 2022). "Dopamine receptor D2 gene (DRD2) and glucocorticoid receptor gene (NR3C1) are implicated in the development of psychosis." (PMID 35968502, 2022).